GNG12 (G protein subunit gamma 12)
Description:
Guanine nucleotide-binding proteins (G proteins) are involved as a modulator or transducer in various transmembrane signaling systems. The beta and gamma chains are required for the GTPase activity, for replacement of GDP by GTP, and for G protein-effector interaction.
Synonyms: HG3A
Tractability: Antibody: UniProt places it where antibodies can reach, with high confidence; its Gene Ontology location is reachable by antibodies, with high confidence. PROTAC: ubiquitination databases record sites on it; its protein half-life has been measured.
Gene: Protein-coding gene on chromosome 1 (67,701,466 to 67,833,476, reverse strand). Ensembl gene ENSG00000172380.
Subcellular location: Cell membrane
Subcellular location (Human Protein Atlas): Mitochondria
Pathways (Reactome):
Signal Transduction: Ca2+ pathway; Extra-nuclear estrogen signaling; G alpha (12/13) signalling events; G alpha (i) signalling events; G alpha (q) signalling events; G alpha (s) signalling events; G alpha (z) signalling events; G beta:gamma signalling through BTK; G beta:gamma signalling through CDC42; G beta:gamma signalling through PI3Kgamma; G beta:gamma signalling through PLC beta; G-protein activation; GPER1 signaling; Glucagon-type ligand receptors
Hemostasis: ADP signalling through P2Y purinoceptor 1; ADP signalling through P2Y purinoceptor 12; Prostacyclin signalling through prostacyclin receptor; Thrombin signalling through proteinase activated receptors (PARs); Thromboxane signalling through TP receptor
Metabolism: Adrenaline,noradrenaline inhibits insulin secretion; Glucagon signaling in metabolic regulation; Glucagon-like Peptide-1 (GLP1) regulates insulin secretion
Neuronal System: Activation of G protein gated Potassium channels; Inhibition of voltage gated Ca2+ channels via Gbeta/gamma subunits; Presynaptic function of Kainate receptors
Cellular responses to stimuli: High laminar flow shear stress activates signaling by PIEZO1 and PECAM1:CDH5:KDR in endothelial cells
Disease: ADORA2B mediated anti-inflammatory cytokines production
Metabolism of proteins: Cooperation of PDCL (PhLP1) and TRiC/CCT in G-protein beta folding
Transport of small molecules: Vasopressin regulates renal water homeostasis via Aquaporins
Gene Ontology:
Molecular function: PDZ domain binding; protein binding; G-protein beta-subunit binding
Biological process: G protein-coupled receptor signaling pathway; signal transduction
Cellular component: extracellular exosome; heterotrimeric G-protein complex; plasma membrane; synapse
Genetic constraint (gnomAD): Loss-of-function variants: 0 observed, 3.77 expected, observed/expected ratio (o/e) 0, 90% interval 0 to 0.79. That is too few expected variants to judge how well the gene tolerates losing a copy. Missense variants: 44 observed, 52.84 expected, observed/expected ratio (o/e) 0.83, 90% interval 0.65 to 1.07. Synonymous variants: 20 observed, 19.46 expected, observed/expected ratio (o/e) 1.03, 90% interval 0.72 to 1.49.
Homologues: Orthologues: chimpanzee GNG12 (100% identical), rabbit GNG12 (100% identical), guinea pig GNG12 (97% identical), mouse Gng12 (96% identical), pig GNG12 (96% identical), rat Gng12 (96% identical), tropical clawed frog gng12 (83% identical), zebrafish gng12b (78% identical), zebrafish gng12a (76% identical). Paralogues in human: GNG7 (72% identical), GNG2 (60% identical), GNG3 (60% identical), GNG4 (56% identical), GNG8 (47% identical), GNG5 (44% identical), GNG10 (43% identical), GNG5B (42% identical), GNG11 (36% identical), GNGT1 (35% identical), GNGT2 (33% identical).
Diseases named in the same sentence as GNG12 in open-access papers:
GNG12 is named in the same sentence as 32 diseases in open-access papers, as found by Europe PMC text mining. Sharing a sentence is not in itself a finding about the gene and the disease. The quoted sentences say what the papers report.
glioma (8 papers, 2018 to 2025). A benign or malignant brain and spinal cord tumor that arises from glial cells (astrocytes, oligodendrocytes, ependymal cells). "Subsequent in vitro experiments were used to validate the proliferation and migration of glioma cells and to explore the potential mechanisms by which GNG12 causes poor prognosis in gliomas." (PMID 35928884, 2022). "The results showed that GNG12 is associated with the infiltration of various immune cells in gliomas, especially B cells, CD4+ T cells, macrophages, and dendritic cells in low-grade gliomas." (PMID 35928884, 2022). "To further understand the pathological mechanism by which GNG12 causes poor glioma prognoses, we applied the GSEA enrichment method." (PMID 35928884, 2022). "In glioma patients, a loss of the GNG12 copy number resulted in decreased infiltration of CD4+ T cells, macrophages, neutrophils, and dendritic cells." (PMID 35928884, 2022). "Univariate and multivariate analyses showed that GNG12 represents a risk factor for glioma occurrence." (PMID 35928884, 2022). "The aim of this study was to comprehensively investigate the relationship between GNG12 and the clinical characteristics and prognosis of glioma patients and reveal the mechanisms causing the malignant process of GNG12." (PMID 35928884, 2022). "The strong association between GNG12 expression levels and the clinical characteristics of glioma patients suggests that GNG12 may be related to the survival prognosis of glioma." (PMID 35928884, 2022). "Considering that the fundamental tumor behavior of the three tumor subtypes are quite different, we speculate that one of the GTPase-associated regulators, GNG12, may have different expression pattern in glioma." (PMID 30322114, 2018). "To explore the relationship between GNG12 and immune cell infiltration, we analyzed the correlation between the expression level of GNG12 and the infiltration level of glioma immune cells using TIMER." (PMID 35928884, 2022). "By activating the PI3K/AKT signaling pathway, miR-876-5p targets GNG12 and contributes to glioma progression." (PMID 36467881, 2022). "First, the survival analysis results showed a significant correlation between high GNG12 expression and reduced survival rates of patients with glioma." (PMID 35928884, 2022). "In grade II and III gliomas and in all samples, the results showed that the survival rate of the GNG12 high expression group was lower than that of the low expression group, regardless of the presence of IDH mutations or 1p/19q co-deletions (–C)." (PMID 35928884, 2022). "The GSE4290 and GSE50161 datasets from the GEO database revealed that the expression level of GNG12 was higher in gliomas than in normal brain tissue." (PMID 35928884, 2022). "We performed a GSEA to further explore the potential mechanisms through which GNG12 affects the malignant biological behavior of glioma cells." (PMID 35928884, 2022). "We further explored the relationship between GNG12 expression levels and the survival prognoses of patients with glioma." (PMID 35928884, 2022). "KM curves were used to assess the correlation between the GNG12 expression and OS of glioma patients." (PMID 35928884, 2022). "The expression of GNG12 in glioma tissues from patients aged >41 years was significantly higher than that in patients aged ≤ 41 years (p =0.009)." (PMID 35928884, 2022). "First, using the GEPIA, GEO, and HPA databases, we found that the expression level of GNG12 was significantly increased in gliomas." (PMID 35928884, 2022). "Knocking down the expression level of GNG12 clearly affected the proliferation and migration abilities of glioma cells." (PMID 35928884, 2022). "Concurrently, we used basic experimental validation to reveal the role of GNG12 in the disease progression of gliomas and some of the mechanisms leading to poor prognoses." (PMID 35928884, 2022). "First, we designed three small molecule-interfering RNAs to inhibit the expression of GNG12 in glioma cells." (PMID 35928884, 2022).
glioma (continued). "Although GSEA only indirectly revealed the mechanism of GNG12 in promoting glioma, these results were based on a comparison of GNG12 with thousands of genes." (PMID 35928884, 2022). "This is the first study to explore the relationship between GNG12 expression levels and the clinical features and prognosis of gliomas." (PMID 35928884, 2022). "First, our study showed that GNG12 is overexpressed in gliomas, and that there are some common clinical characteristics and molecular staging that are closely related to GNG12 expression." (PMID 35928884, 2022). "The diminished migratory capacity of glioma cells within 48 h of GNG12 downregulation was ultimately verified using a cell scratch healing assay." (PMID 35928884, 2022). "Subsequently, the relationship between GNG12 expression levels and patients clinical characteristics with glioma was analyzed." (PMID 35928884, 2022). "In conclusion, this study has objectively verified that GNG12 contributes to glioma development and poor prognoses by regulating cell adhesion molecular pathways." (PMID 35928884, 2022). "To probe the specific mechanism by which GNG12 leads to poor prognosis of glioma, we verified the predicted results of GSEA in WB experiments." (PMID 35928884, 2022). "In summary, GNG12 can be used as a novel biomarker for the early diagnosis of human gliomas and as a potential therapeutic target." (PMID 35928884, 2022). "Through the analysis of publicly available single-cell RNA sequencing data, we found that cells with high GNG12 expression were mainly glioma cells, which supported this conclusion." (PMID 34222011, 2021). "GNG12 (rank 6), as another optimal biomarker, contributes to the distinction of different glioma subtypes." (PMID 30322114, 2018). "Our RT-qPCR and IHC results further verified that GNG12 was consistently overexpressed in gliomas." (PMID 35928884, 2022). "Therefore, this study utilized a multi-omics approach and comprehensive bioinformatics analysis to explore the relationship between GNG12 and the malignant biological behavior of gliomas." (PMID 35928884, 2022). "A high expression level of GNG12 often predicts a poor prognosis in patients with gliomas." (PMID 35928884, 2022). "To further validate the effect of GNG12 on glioma, we performed a series of in vitro experiments." (PMID 35928884, 2022). "In conclusion, it is possible that a high GNG12 expression leads to reduced immune cell infiltration and may be an important factor contributing to poor prognoses in patients with glioma." (PMID 35928884, 2022). "Additionally, several in vitro experiments demonstrated that down-regulation of GNG12 expression can inhibits the proliferation and migration capacity of glioma cells." (PMID 35928884, 2022). "The expression level of GNG12 was positively correlated with the WHO grade of glioma (P < 0.001)." (PMID 35928884, 2022). "These combined results suggest that GNG12 may interfere with the tumor microenvironment of gliomas by affecting the infiltration of various immune cells, which in turn leads to the development and poor prognosis of gliomas." (PMID 35928884, 2022). "In this study, we identified GNG12 as a novel oncogene elevated in gliomas." (PMID 35928884, 2022). "Ultimately, the results for the GSEA and WB experiments revealed that GNG12 may promote the malignant progression of gliomas by regulating the cell adhesion molecule cell signaling pathway." (PMID 35928884, 2022). "We conducted a series of experiments to explore the effect of GNG12 on gliomas." (PMID 35928884, 2022). "Moreover, long non‐coding gng12 RNAs are highly expressed in glioma tissues and its downregulation inhibits proliferation, migration and epithelial‐mesenchymal transition of glioma cells." (PMID 35194846, 2022). "Reducing GNG12 expression inhibits the proliferation and migration of glioma cells." (PMID 35928884, 2022).
glioma (continued). "The in vitro results showed that downregulating GNG12 expression level inhibited the proliferation and migration ability of gliomas, which may represent a potential link between poor glioma prognoses and GNG12." (PMID 35928884, 2022). "This suggests that GNG12 may help regulate the cell adhesion molecule pathway involved in the malignant process of gliomas." (PMID 35928884, 2022). "Therefore, we used in vitro cellular assays to verify that the knockdown of GNG12 significantly inhibited the proliferation and migration abilities of glioma cell lines and explored some of the molecular mechanisms of GNG12 in cell signaling pathways." (PMID 35928884, 2022). "In addition, recurrent gliomas had higher GNG12 expression levels than primary gliomas, which explains why patients with recurrent gliomas had a worse prognosis (p<0.05)." (PMID 35928884, 2022). "Multiple findings indicate that GNG12 not only is a biomarker for glioma subtypes but also may promote tumour progression and that GNG12, which targets miR-876-5p, promotes the malignant progression of gliomas by increasing PI3K/AKT signalling activity." (PMID 40594780, 2025). "Finally, we excluded the influence of random factors via univariate and multivariate analyses, from which we reached the scientific conclusion that a high GNG12 expression level may serve as an important predictor of poor prognoses in patients with glioma." (PMID 35928884, 2022). "Thus, it is important to further explore the role of GNG12 in gliomas." (PMID 35928884, 2022). "Furthermore, GNG12 may regulate glioma development and progression by participating in the cell adhesion molecule pathway." (PMID 35928884, 2022). "Therefore, our results indicate that GNG12 may serve as a biomarker for glioma, especially in the five-year OS group." (PMID 35928884, 2022). "GNG12 influences a variety of tumors; however, its relationship with glioma remains unclear." (PMID 35928884, 2022). "GNG12 might play a distinct role in the formation of immunosuppressive phenotype of glioma." (PMID 34222011, 2021). "And GNG12 could be treated as a potential effector in immunosuppressive phenotype of glioma." (PMID 34222011, 2021). "These cellular signaling pathways showed significant different enrichment rates in samples from patients showing the GNG12 high-expression phenotype based on NES, NOM P-values, and FDR values, thus indicating a potential role for GNG12 in developing glioma." (PMID 35928884, 2022). "In summary, our targeted downregulation of GNG12 expression levels in glioma cell lines resulted in a certain degree of diminished proliferation and migration; therefore, we speculate that a high GNG12 expression may be an important factor in the poor prognoses of glioma patients." (PMID 35928884, 2022). "The positive clustering results of this study might be attributed to some characteristics of glioma tissue, such as the glioma-specific 1p19q co-deletion that affected the expression of GNB1, GNG5, GNG7, GNGN8, and GNG12." (PMID 34222011, 2021). "Interestingly, our study’s GNG12 expression was positively correlated with immune checkpoints, including PD-1, PDL-1, and PD-L2 in gliomas; therefore, we can combine this gene with immune checkpoint inhibitors to provide a novel glioma immunotherapy." (PMID 35928884, 2022). "However, the relationship between GNG12 and glioma prognoses as well as related clinical features has not received much attention." (PMID 35928884, 2022). "The roles of FZD8, GNG12, GNB2 have not been fully illustrated in gliomas and needs further investigation." (PMID 35116059, 2021).
osteosarcoma (7 papers, 2021 to 2024). A usually aggressive malignant bone-forming mesenchymal neoplasm, predominantly affecting adolescents and young adults. "We aimed to identify an association between GNG12 and osteosarcoma based on the Gene Expression Omnibus and the Therapeutically Applicable Research to Generate Effective Treatments (TARGET) databases." (PMID 34691083, 2021). "Although these studies suggest an important role for GNG12 in cancer progression, we currently know little about the underlying mechanisms and function of this protein in osteosarcoma progression and immunology." (PMID 34691083, 2021). "Second, to clarify the function of GNG12, DEGs, and hub genes in osteosarcoma, a clean loss-of-function and gain-on-function study with tissue- and cell-type specificities remains warranted." (PMID 34691083, 2021). "Our results demonstrated that low GNG12 expression is a potential biomarker of osteosarcoma, linked to poor prognosis." (PMID 34691083, 2021). "Low GNG12 expression was associated with a poor prognosis of osteosarcoma." (PMID 36405685, 2022). "Notably, GNG12 showed a significant positive correlation with a variety of drugs, which accord closely with the findings of the low expression associated with poor prognosis in osteosarcoma." (PMID 36405685, 2022). "GNG12 was a highly effective biomarker for osteosarcoma; high GNG12 related to a better prognosis and lower M1 and M2 scores." (PMID 36814925, 2023). "We found an AUC of 0.920, indicating that GNG12 expression was an excellent biomarker for distinguishing osteosarcoma from normal tissue." (PMID 34691083, 2021). "In conclusion, GNG12 mRNA and protein expression were downregulated in osteosarcoma, a change that was related to poor prognosis." (PMID 34691083, 2021). "We used 78 patients with osteosarcoma as a validation cohort to confirm the prognostic reliability of GNG12." (PMID 34691083, 2021). "We provided important evidence supporting GNG12 as a biomarker for osteosarcoma prognosis and highlighting its potential as a target for immunotherapy." (PMID 34691083, 2021). "Meanwhile, researchers found that lncRNA HOTTIP can decoy miR-27a-3p to promote G protein subunit gamma 12 (GNG12)-mediated metastasis in osteosarcoma." (PMID 35071016, 2021). "We also collected osteosarcoma samples to evaluate GNG12 predictive ability on survival and prognosis, using immunohistochemistry, histochemistry score (H-Score) analysis, and receiver operating characteristic (ROC) analysis." (PMID 34691083, 2021). "Analysis of data from GEO indicated that GNG12 expression was significantly downregulated in osteosarcoma tissues compared with normal samples." (PMID 34691083, 2021). "Second, our outcomes were validated in a set of 78 patients with osteosarcoma, using an H-score to evaluate GNG12 expression in osteosarcoma tissue." (PMID 34691083, 2021). "This study identified GNG12 as a potential biomarker for osteosarcoma prognosis, highlighting its potential as an immunotherapy target." (PMID 34691083, 2021). "Taken together, our research and previous studies provided insight on GNG12’s role in cancer pathogenesis and demonstrated that the protein is a potential biomarker of osteosarcoma." (PMID 34691083, 2021). "GNG12 expression was significantly different between the standard samples (n = 15) and osteosarcoma samples (n = 103)." (PMID 34691083, 2021). "Patients with osteosarcoma were divided into high and low GNG12 mRNA-expression groups; differentially expressed genes were identified as GNG12-related genes." (PMID 34691083, 2021). "This study thus aimed to determine the role of GNG12 in patients with osteosarcoma." (PMID 34691083, 2021). "Finally, we confirmed the feasibility of GNG12 as a biomarker in our collected osteosarcoma samples." (PMID 34691083, 2021). "Functional analyses indicated that GNG12 may promote osteosarcoma through regulating the endoplasmic reticulum." (PMID 34691083, 2021).